EPHA2 (EPH receptor A2)
Diseases named in the same sentence as EPHA2 in open-access papers (continued):
Sharing a sentence is not in itself a finding about the gene and the disease.
oral cancer (3 papers, 2020 to 2025). "EphA2 expression was correlated with shorter survival periods and was a significant prognostic factor in oral cancer." (PMID 40421081, 2025). "Previous studies have shown that IL-17F suppresses VM in oral tongue squamous cell carcinoma; HIF-1α/EphA2/Laminin-5γ2 axis downregulation inhibits hypoxia-induced VM in oral cancer; SOX7 inhibits VM by downregulating VE-cadherin in OSCC." (PMID 41502523, 2025). "The results demonstrated that elevated levels of EphA2 and VEGF, as well as increased microvessel density (MVD) and advanced TNM (tumor size, nodal spread, metastasis) stage, were associated with shorter survival periods and served as significant negative prognostic factors in oral cancer." (PMID 40421081, 2025).
oral squamous cell carcinoma (3 papers, 2021 to 2024). "Ephrin receptor A2 (EphA2), a member of the Ephrin receptor family, is closely related to the progression of oral squamous cell carcinoma (OSCC)." (PMID 38916835, 2024).
parasitemia (3 papers, 2016 to 2025). "Alternatively, ligands that bias EphA2 signaling toward promoting receptor endocytosis could be used for delivery of conjugated drugs into EphA2-expressing cells or for depletion of cell-surface EphA2 in order to inhibit parasitic infections." (PMID 40049409, 2025).
prostate tumor (3 papers, 2007 to 2023). "Nearly 44% (23/52, sample ID labeled in red) of the prostate tumors showed the 'dasatinib-responsive' expression patterns (that is, low AR and PSA and high uPA, EphA2 and/or CK5)." (PMID 18047674, 2007). "In the earliest studies, it was shown how EphA2 activation without degradation by the means of low concentrations of ephrin-A1-Fc was a key way of efficiently inhibiting prostate tumor growth, at least in vitro." (PMID 37895923, 2023).
prostatic intraepithelial neoplasia (3 papers, 2005 to 2023). "It is interesting to note that increased expression of another ephrin receptor, EPHA2, has been demonstrated in prostatic intraepithelial neoplasia, and shown to be associated with neoplastic transformation." (PMID 16042785, 2005).
renal carcinoma (3 papers, 2019 to 2022). A carcinoma arising from the epithelium of the renal parenchyma or the renal pelvis. "The enhanced phosphorylation of EGFR, MET, and EPHA2/B1 upon FLCN loss is interesting in light of previous studies that linked these kinases to renal cancer." (PMID 35863698, 2022). "In conclusion, our findings indicate that YB1 and EphA2 levels are highly expressed in renal cancer cells and tissues and further increase in SUN-resistant cells." (PMID 32814829, 2020). "YB1 not only restored EphA2 protein expression but also rescued the metastatic phenotype of EphA2 knockdown in human renal cancer cells." (PMID 32814829, 2020). "Our previous study found that EphA2 expression was elevated and that high EphA2 expression contributed to cell migration and invasion in renal cancer." (PMID 32814829, 2020). "Subsequently, we demonstrated that knockdown or overexpression of YB1 could downregulate or upregulate EphA2 expression in human renal cancer cells, respectively." (PMID 32814829, 2020). "Our findings indicated that both YB1 and EphA2 could promote the invasion and metastasis of renal cancer cells, but the regulatory network between them remained unclear." (PMID 32814829, 2020). "Knockdown of EphA2 expression inhibited cell migration and invasion in human renal cancer cells." (PMID 32814829, 2020). "Moreover, both YB1 and EphA2 have been reported to promote cell metastasis of renal cancer in vitro." (PMID 32814829, 2020). "Our results suggest that the expression levels of YB1 and EphA2 are upregulated in SUN-resistant cells and that their high expression levels mediate the resistance of renal cancer cells to SUN." (PMID 32814829, 2020). "EphA2 knockdown by shRNA counteracts YB1-mediated renal cancer SUN resistance in vitro, and this effect is also confirmed by EphA2 small molecule inhibitor ALW." (PMID 32814829, 2020). "However, the roles of EphA2 and its association with YB1 in SUN resistance have not been reported in renal cancer." (PMID 32814829, 2020).
skin cancer (3 papers, 2010 to 2020). "The EPHA2 gene, a risk factor for age-related cataract, is overexpressed in several types of cancers including skin cancer, mainly malignant melanoma." (PMID 32460312, 2020). "In contrast to this pro-oncogenic role for EPHA2, EPHA2 knockout mice are more susceptible to chemically-induced skin cancer, which indicates that in some circumstances EPHA2 can suppress tumorigenesis." (PMID 20979646, 2010). "UVR from sunlight and EPHA2 gene play important roles, both in age-related cataract and skin cancer." (PMID 32460312, 2020). "Regardless of the mechanism, EPHA2 is involved in skin cancer." (PMID 32460312, 2020).
small cell lung carcinoma (3 papers, 2020 to 2022). Small cell lung cancer (SCLC) is a highly aggressive malignant neoplasm, accounting for 10-15% of lung cancer cases, characterized byrapid growth, and early metastasis. "For example, EphA2 expression is elevated in small-cell lung cancer, and suppression of EphA2 has the ability to restrain cell proliferation." (PMID 36090890, 2022).
squamous cell lung carcinoma (3 papers, 2013 to 2021). A carcinoma arising from squamous bronchial epithelial cells. "The mutation G391R in EphA2 confers susceptibility to treatment with rapamycin (Rapamune, Pfizer, NY, USA), an mTOR inhibitor and was seen in 7% of squamous cell lung cancers vs. 0% of other histologies in one report." (PMID 23936763, 2013). "A G391R mutation in the EphA2 gene was recurrent in lung squamous cell carcinoma and associated with increased phosphorylation of two serine residues within mTOR—it has been suggested that this may be functionally important for EphA2’s invasive signals." (PMID 33430066, 2021). "Mutations in EphA2 although over all rare, are more common in lung squamous cell cancer histology." (PMID 23936763, 2013).
Stroke (3 papers, 2013 to 2025). Sudden impairment of blood flow to a part of the brain due to occlusion or rupture of an artery to the brain. "EPHA2 was significantly associated with both dementia and stroke, and their effect directions were consistent with the MR findings." (PMID 39818967, 2025). "Our findings that MMP-9 levels were reduced in EphA2−/− mice are consistent with their milder post-stroke BBB damage and subsequent leakage, as compared to WT counterparts." (PMID 23308246, 2013). "Furthermore, EphA2−/− mice also had markedly less Evans Blue leakage than WT controls in the ipsilateral stroke brain tissue exudates, consistent with less BBB damage following cerebral I/R." (PMID 23308246, 2013). "Thus, reduced post-stroke BBB damage observed in EphA2−/− mice correlates with their improved functional outcomes." (PMID 23308246, 2013). "Similarly the EphA2−/− mice had significantly reduced post-stroke edema and immune cell infiltrates." (PMID 23308246, 2013). "Although total EphA2/3/4/5 phosphorylation increases during the first week after middle cerebral artery occlusion (MCAO), EphA4 phosphorylation relative to total EphA4 protein levels remained unaltered during the acute, subacute and chronic phase after photothrombotic stroke." (PMID 31814004, 2020).
asthma (2 papers, 2021 to 2022). "Mechanistically, Y132 phosphorylation is induced by Ephrin type-A receptor 2 (EphA2), which is selectively expressed in AECs and contributes to inhibiting the NLRP3 inflammasome in an ovalbumin‐induced asthma model." (PMID 33627128, 2021).
bone tumor (2 papers, 2012 to 2021). "Thus, currently available targeted cancer drugs, such as inhibitors of the ErbB or VEGF receptors, or dasatanib with affinity for EphA2, could be further evaluated as novel therapeutics for pediatric bone tumors." (PMID 23227212, 2012). "Thus, currently available targeted cancer drugs such as inhibitors of the EphA2, VEGF or ErbB receptors could be tested as novel therapeutics for pediatric bone tumors." (PMID 23227212, 2012).
Breast Invasive Carcinoma (2 papers, 2022 to 2025). "Likewise, targeted treatment against EPHA2 could be of value in combination with tamoxifen or trastuzumab in mutually EPHA2- and ER- or EPHA2- and HER2-positive subgroups of invasive breast cancer patients, respectively." (PMID 35204461, 2022).
Chlamydia infection (2 papers, 2015 to 2023). "Chlamydia infection-associated activation of PI3K has been shown to depend on the host cell surface tyrosine kinase EphrinA2 receptor (EphA2)." (PMID 37374883, 2023). "Noteworthily, EphA2 knockdown promoted cell apoptosis, indicating that EphA2-mediated signaling plays a supportive role in Chlamydia infection-induced apoptosis resistance." (PMID 37374883, 2023).
choroidal melanoma (2 papers, 2015 to 2017). Malignant tumor of melanocytes of the choroid. "Others have reported that inhibition of EphA2 expression may down-regulate expression of MMP-9 in a murine choroidal melanoma model, and PI3K may be the mediator in this regulatory pathway." (PMID 25788424, 2015).
chronic lymphocytic leukemia (2 papers, 2017 to 2021). "In chronic lymphocytic leukemia cells, ephrin-A4 activation by EphA2-Fc significantly reduced cell adhesion to fibronectin-, collagen-, laminin-, ICAM-1-, and VCAM-1-coated surfaces." (PMID 28851287, 2017).
chronic rhinosinusitis (2 papers, 2024 to 2025). Chronic form of sinusitis. "As ephrinA1/ephA2 signaling affects rhinovirus-induced innate immunity in human sinonasal epithelial cells, clinical studies have found that the expression of the ephrin A1 receptor is increased in patients with chronic rhinosinusitis." (PMID 40873739, 2025).
clear cell renal cell carcinoma (2 papers, 2014 to 2024). "In this study, mRNA and protein expression of the receptors EPHA1 and EPHA2 as well as of their ligand EFNA1 and their prognostic relevance in clear cell renal cell carcinoma was evaluated." (PMID 25025847, 2014).
colitis (2 papers, 2020 to 2021). Inflammation of the colon. "The assessment of the changes induced by UniPR1331 and EphA2 on mRNA levels of EphA2 and ephrin-A1 in colitis will contribute to further enrich the scenario." (PMID 34074058, 2021).
Coronary Artery Disease (2 papers, 2021 to 2025). "However, the roles of circulating PGRN and EphA2 in coronary artery disease (CAD) remain unclear." (PMID 33968283, 2021).
COVID-19 (2 papers, 2021 to 2024). A disease caused by infection with severe acute respiratory syndrome coronavirus 2. "Our results showed that ICU COVID-19 patients who eventually died had elevated EphA2 levels compared to ICU patients who survived their illness." (PMID 34359331, 2021).
follicular lymphoma (2 papers, 2016). Follicular lymphoma is a form of non-Hodgkin lymphoma characterized by a proliferation of B cells whose nodular structure of follicular architecture is preserved. "The truncated form of EPHA7 (EPHA7TR) was revealed as a soluble tumor suppressor for follicular lymphoma by inhibiting EPHA2 signaling, which makes EPHA7 a promising targeted therapeutic polypeptide." (PMID 27681722, 2016).
HCMV infection (2 papers, 2023 to 2025). "Pharmacological or genetic inhibition of EphA2 has been shown to reduce HCMV infection and to attenuate tumor progression, highlighting its potential as a therapeutic target." (PMID 41471245, 2025). "Two independent siRNAs both can reduce the EphA2 expression as well as the HCMV infection efficiency." (PMID 37146061, 2023). "Consistently, EphA2 siRNAs also significantly decreased the EphA2 protein expression and HCMV infection." (PMID 37146061, 2023). "Antibody against EphA2 or rabbit IgG control was pre-incubated with U138 cells prior to HCMV infection, and infection efficiency was measured by flow cytometry." (PMID 37146061, 2023). "EphA2 protein and HCMV infection were remarkably decreased in U138 cells transduced with either sgA2-1# or sgA2-2# sgRNA." (PMID 37146061, 2023). "Notably, EphA2 knockdown resulted a more than 50 percent reduction of HCMV infection." (PMID 37146061, 2023). "Furthermore, to determine if antibodies against EphA2 ectodomain could block HCMV infection, we generated a rabbit polyclonal antibody against EphA2." (PMID 37146061, 2023). "EphA2 has been identified as a critical host factor that mediates HCMV entry and membrane fusion in GB cells, thereby facilitating HCMV infection." (PMID 41471245, 2025). "We have identified that EphA2 could interact with HCMV gH/gL complex, but not gB to promote cell-cell fusion, which may support the development of gH/gL vaccines or drugs targeting gH/gL to block the HCMV infection." (PMID 37146061, 2023).
Hypertension (2 papers, 2012 to 2022). The presence of chronic increased pressure in the systemic arterial system. "The current study first determined the features of circulating EphA2 levels in patients with hypertension and analyzed the association between renal function and EphA2 levels." (PMID 36553030, 2022). "Circulating EphA2 levels were significantly higher in patients with renal function decline compared with patients with normal kidney function, suggesting the potential diagnostic efficiency of circulating EphA2 levels in evaluating kidney function in patients with hypertension." (PMID 36553030, 2022). "High circulating EphA2 levels have potential application as a clinical biomarker for the presence of CKD in patients with hypertension." (PMID 36553030, 2022). "This study aims to develop and validate a sensitive and specific ephrin type-A receptor 2 (EphA2) enzyme-linked immunosorbent assay (ELISA) for human serum, and determine whether its results correlate with traditional renal measures in patients with hypertension." (PMID 36553030, 2022). "The novel ELISA of the current study was validated and used to measure circulating EphA2 levels in 80 hypertensive patients with and without kidney function decline (eGFR less than 60 mL/min/1.73 m2)." (PMID 36553030, 2022). "Clinically used as an α1-adrenoreceptor antagonist (Cardura®) for treating hypertension and benign prostate hyperplasia, doxazosin activated EphA2 independent of α1-adrenoreceptor." (PMID 22916121, 2012).
Insulin resistance (2 papers, 2023 to 2024). Increased resistance towards insulin, that is, diminished effectiveness of insulin in reducing blood glucose levels. "However, the implications of increased EphA2 levels in the HepG2 IGF1R KO cell model with induced insulin resistance remain unknown." (PMID 39572596, 2024). "Activation of the ERK pathway by insulin was responsible for upregulating EphA2 levels, and this mechanism was independent of insulin resistance." (PMID 39572596, 2024). "In addition, several energy metabolic processes, such as the PI3K-Akt pathway (EPHA2, FLT4, ITGA5, and LPAR6), cholesterol metabolism (APOE and CD36), and insulin resistance (FOLR1, CALM14, and PPP1R3A), were enriched in ApoE4 mice." (PMID 36720919, 2023). "However, the regulation of EphA2 was independent of insulin resistance." (PMID 39572596, 2024). "At the proteome level, the ephrin type-A receptor 2 (EphA2) showed an insulin-induced increase in expression, which occurred through the ERK signaling pathway and was concordantly independent of insulin resistance." (PMID 39572596, 2024).
malignant mesothelioma (2 papers, 2012). A malignant neoplasm of the pleura or peritoneum, arising from mesothelial cells. "Previously we have reported that EphA2 is over expressed in malignant mesothelioma cells (MMC) and posttranslational silencing of EphA2 significantly suppresses the proliferation and haptotactic migration of MMC." (PMID 22824143, 2012).
malignant pleural mesothelioma (2 papers, 2019 to 2020). A malignant neoplasm that arises from mesothelial cells in the pleura and shows a diffuse growth pattern. "Besides, ephA2/ephirnA1 signalling regulates miR‐302b expression and attenuates malignant pleural mesothelioma cell growth." (PMID 32233022, 2020).
metastasis (2 papers, 2019 to 2021). The spread or migration of cancer cells from one part of the body (where they first appeared) to another. "Our data with 144 patient tissues showed higher levels of EphA2 to be associated with advanced cancer stages, tumor size, lymph node metastasis, and lymphovascular invasion." (PMID 30833656, 2019). "EphA2 protein expression was positively correlated with CDK6 protein expression, invasion depth, lymph node metastasis and clinicopathological stage (P < .05)." (PMID 33586348, 2021).
Microcornea (2 papers, 2010 to 2021). A congenital abnormality of the cornea in which the cornea and the anterior segment of the eye are smaller than normal. "For example, mutations in multiple genes have been associated with cataract plus microcornea (e.g., MAF, CRYAA, and GJA8), posterior polar cataract (e.g., PITX3, EPHA2, CHMP4B, and NF2), or sutural cataract (e.g., BFSP2, CRYAB, and NHS)." (PMID 21042563, 2010).
pulmonary fibrosis (2 papers, 2021 to 2025). Chronic progressive interstitial lung disorder characterized by the replacement of the lung tissue by connective tissue, leading to progressive dyspnea, respiratory failure, or right heart failure. "In mice treated with BLM, atRA attenuated the upregulation of IL-17A, IL-10, IL-6, EphA2, EphriA1, PI3K 110γ, Akt, IL-6, TNF-α, and TGFβ1, which reduced pulmonary fibrosis and significantly alleviated lung fibrosis." (PMID 40508111, 2025).
reovirus infection (2 papers, 2022 to 2023). "Immunofluorescence imaging revealed endogenous NLRP3 colocalized with EphA2 in the cytosol, and this colocalization was enhanced with reovirus infection." (PMID 38022631, 2023). "Furthermore, a murine model of reovirus infection conducted with wild-type and EphA2-knockout mice confirmed the role of EphA2 in the regulation of inflammasome activation and the resulting lung inflammation." (PMID 38022631, 2023).
sarcoidosis (2 papers, 2018 to 2020). Sarcoidosis is a multisystemic disorder of unknown cause characterized by the formation of immune granulomas in involved organs. "Remarkably, in addition to NOD2 2722G > C, three single nucleotide variants for the IL17RA, KALRN and EPHA2 genes were found in the family X patients with sarcoidosis." (PMID 29554915, 2018). "Taken together, our data suggest a functional and pathogenic link between EPHA2, KALRN and IL17RA in the occurrence of the disease of family X sarcoidosis patients, acting in addition to the NOD2 functional defect." (PMID 29554915, 2018). "Our finding further establishes that the NOD2 2722G > C variant in combination with variants for IL17RA, EPHA2 and KALRN genes could play a significant role in the development of sarcoidosis." (PMID 29554915, 2018). "Combination of polymorphisms in the NOD2, IL17RA, EPHA2 and KALRN genes could play a significant role in the development of sarcoidosis by maintaining a chronic pro-inflammatory status in macrophages." (PMID 29554915, 2018).